ANGPTL4 (angiopoietin like 4)
Diseases named in the same sentence as ANGPTL4 in open-access papers (continued):
Sharing a sentence is not in itself a finding about the gene and the disease.
breast cancer (continued). "Interestingly, PPARα has been identified as the primary PPAR subtype involved in the obesity-induced upregulation of ANGPTL4 expression in breast cancer cells." (PMID 40616161, 2025). "Furthermore, we stratified bulk breast cancer data from TCGA into low and high ANGPTL4 expression groups and conducted GSEA analysis." (PMID 40616161, 2025). "Previous studies have shown that ANGPTL4 promotes metastasis upon breast cancer cell injection, supports energy production during epithelial-to-mesenchymal transition (EMT), and favors proliferation, migration, and invasion in non-small cell lung cancer (NSCLC) cells." (PMID 40616161, 2025). "Additionally, ANGPTL4 has been shown to activate FAK signaling in breast cancer cells treated with adipocyte-conditioned medium." (PMID 40616161, 2025). "Bioluminescence imaging revealed that ANGPTL4 knockdown significantly reduced pulmonary metastasis compared to the negative control group, while ectopic ANGPTL4 expression accelerated lung metastasis of breast cancer." (PMID 40616161, 2025). "In breast cancer, ANGPTL4 expression correlates to tumor cell extravasation." (PMID 41404065, 2025). "Meaningfully, ANGPTL4 expression was also elevated in breast cancer tissues from obese patients." (PMID 40616161, 2025). "However, some ccRCC tumors are HIF-2 exclusive, which points out a possible function of HIF-2 in regulating ANGPTL4 expression, which has also been shown in breast cancer models through an HIF-2-dependent upregulation of specific lncRNA." (PMID 40723247, 2025). "Currently, there are limited studies reporting how ANGPTL4 regulates TME in breast cancer." (PMID 39910592, 2025). "Similarly, ANGPTL4 has been shown to enhance breast cancer cell invasion and metastasis to the lung." (PMID 39456610, 2024). "Avalle and his colleagues found that STAT3 could promote the secretion of ANGPTL4 to accelerate cell growth in breast cancer." (PMID 38212795, 2024). "Blocking the expressions of ANGPTL4 inhibits lung metastasis of breast cancer cells." (PMID 38245723, 2024). "Consequently, adipocyte-derived ANGPTL4 promotes obesity-driven breast cancer progression and angiogenesis." (PMID 36670988, 2023). "Moreover, angiopoietin-like 4 reportedly plays a role in angiogenesis and breast cancer progression." (PMID 36090993, 2022). "In addition to VEGF, angiopoietin-like 4 (ANGPTL4) has been investigated in implanted E0071 mammary tumors." (PMID 35186923, 2022). "Moreover, in circulating tumor cells from women with breast cancer, ANGPTL4 copy number gain was found to be part of a signature of tumor aggressiveness and increased metastatic potential." (PMID 36074318, 2022). "In mice, obesity-related inflammation causes an increase in IL-1β production, which then promotes angiogenesis and tumor progression by upregulating Angptl4, thereby setting the rationale for future exploitation of this factor as a potential therapeutic target for obese breast cancer patients." (PMID 36074318, 2022). "Consequently, the pharmacological inhibition of PPARα reduced ANGPTL4 expression, which is involved in adipose-tissue-induced β-oxidation, proliferation, and the invasion of breast cancer cells." (PMID 35954274, 2022). "Similarly, frequency of IGF-1 immunoreactivity among different molecular subtypes of breast carcinoma was mimicking that observed in ANGPTL4." (PMID 35366286, 2022). "In addition, the transforming growth factor-beta 2 (TGF-β2)/ANGPTL4 axis was reported to be responsible for breast cancer brain metastasis in a mouse model." (PMID 33726754, 2021). "To ask whether CrEL-induced ANGPTL4 is clinically relevant, we examined the lipid profiles of patients with breast cancer." (PMID 34646996, 2021). "Similarly, CrEL also enhanced aerobic glycolysis and increased the expression of ANGPTL4 in breast cancer cell lines MDA-MB-231 and MCF7." (PMID 34646996, 2021).
breast cancer (continued). "Since ANGPTL4 is cleaved into nANGPTL4 and cANGPTL4 fragments, we aimed to decipher the biological effect of each of the two fragments when expressed by 4T1 murine breast cancer cells." (PMID 32405335, 2020). "In addition, previous studies showed that the copy number of ANGPTL4 increased in the circulating tumor cells of patients and was related to increased aggressiveness in breast cancer." (PMID 32928141, 2020). "First, we determined the expression of ANGPTL4 in different breast cancer cell lines." (PMID 32928141, 2020). "Additionally, ANGPTL4 overexpression was related to a short DFS in a basal breast cancer type commonly found in young women." (PMID 32928141, 2020). "ANGPTL4 mediates TGF‐β priming for mammary tumor dissemination to the lungs." (PMID 33377651, 2020). "This provides groundwork to target ANGPTL4 as a treatment for breast cancer brain metastases." (PMID 31602400, 2019). "In addition, performing a whole genome expression profile on circulating tumor cells in breast cancer patients, it has been identified a signature of genes, including ANGPTL4 that distinguished the tumor-aggressiveness of the breast cancer." (PMID 29389861, 2018). "Another report also suggests that TGFβ primes human breast cancer cells to lung metastasis through the activation of Angiopoietin-like 4 (ANGPTL4) which disrupts endothelial cell-cell junctions, thus permitting metastatic breast cells to extravasate and initiate metastatic colonies in the lung." (PMID 30463358, 2018). "Moreover, the induction of ANGPTL4 expression by oleate was also detected in other cancer cell types, including breast cancer cells." (PMID 29163362, 2017). "Interestingly, some of these genes have also been linked to cancer progression, for example HIF1A-dependent upregulation of PDGFB and ANGPTL-4 promotes metastasis of hypoxic breast cancer cells." (PMID 28077088, 2017). "The role of ANGPTL4 in the bone metastasis of breast cancer cells has yet to be determined." (PMID 27706047, 2016). "Also, TGFβ in the tumor microenvironment is able to prime breast cancer cells for pulmonary metastasis by inducing angiopoietin-like 4 (ANGPTL4) secretion which facilitates retention of cancer cells to the lungs." (PMID 25883652, 2015). "ANGPTL4 promotes metastasis in several types of cancers including breast cancers and esophageal squamous cell carcinoma, but the surface receptor for ANGPTL4 remains unknown." (PMID 26056041, 2015). "Overexpression of ANGPTL4 was associated with inferior outcome for young women with basal breast tumors; the same held true for the keratins (KRT5, KRT6A, and KRT6B) among young women with HER2-enriched breast cancer." (PMID 25999348, 2015). "Methylation of ANGPTL4 gene has also been found in primary breast cancer." (PMID 25148701, 2014). "The mechanism of the TGF-β induced lung metastasis in breast cancer is related to the induction of the angiopoietin-like 4 (ANGPTL4) gene by TGF-β Smad-dependent signaling in the primary tumor, enabling the cells which leave the breast to disrupt the lung capillary walls." (PMID 24891760, 2014). "Overall, our analysis reveals a significant inverse correlation between WWOX and ANGPTL4 transcript levels in breast cancer patient samples and that tumors with the WWOXlo/ANGPTL4hi signature correlate with breast cancer subtypes characterized by poor prognosis." (PMID 24330518, 2013). "Furthermore, ANGPTL4 may interact with other inflammatory mediators as demonstrated in obesity-related breast cancer, e.g., by the upregulation of IL-1β in inflammatory conditions." (PMID 40006981, 2025). "To further assess whether ANGPTL4 and its downstream signaling pathways influence clinical outcomes in human breast cancer, we analyzed several annotated breast tumor datasets to compare ANGPTL4 expression across different breast cancer subtypes and among patients with varying body mass index (BMI)." (PMID 40616161, 2025).
breast cancer (continued). "Additionally, we noted a trend suggesting that elevated ANGPTL4 expression might positively influence the OS of breast cancer patients." (PMID 40340806, 2025). "Importantly, a fragment of the intracellular domain of HER2, termed 611-CTF (carboxy terminal fragment), can constitutively homodimerize and regulate MET, EPHA2, matrix metalloproteinase 1, interleukin 11, angiopoietin-like 4, and different integrins, promoting mammary tumor growth and metastasis." (PMID 37138747, 2023). "Similarly, ANGPTL4 overexpression increased breast cancer lung metastasis by MDA-MB-231 cells." (PMID 28458654, 2017). "Moreover, it has been demonstrated that Angptl4 disrupts vascular endothelial cell-cell junctions and promotes lung metastasis of breast cancer cells expressing transforming growth factor-β, while preventing metastasis of melanoma cells and also inhibiting angiogenesis." (PMID 23617883, 2013). "For example, CAV1, down-regulated in the cancer samples, was found to inhibit breast cancer growth and metastasis; the down-regulation of PPARG is associated with local recurrence and metastasis in breast cancer; and ANGPTL4 may act as a regulator of angiogenesis." (PMID 21060876, 2010). "In obesity-driven breast cancer, NLRC4 inflammasome activation in tumor-infiltrating macrophages enhances ANGPTL4 expression in mammary adipocytes via IL-1β, thereby driving tumor progression and angiogenesis." (PMID 40723247, 2025). "Specifically, ANGPTL4 and KLF4 were both highly expressed in metastatic breast cancer, and further co-expression analysis indicated that ANGPTL4 and KLF4 were simultaneously expressed in breast cancer tissue microarray (R = 0.3610, p = 0.0183, n = 44)." (PMID 40616161, 2025). "ANGPTL4, PIEZO2, SCNN1A, LTBP1, and SerpinB2 promote the survival of breast cancer cells in the brain microenvironment." (PMID 37108248, 2023). "This is achieved through the secretion of ANGPTL4, MMP13, and STC1 by CAFs, which promotes breast cancer growth." (PMID 38273859, 2023). "The co-culture of adipocytes and breast cancer cell induces the expression of genes involved in inflammation and lipid metabolism (IL1, PLIN2, ANGPTL4)." (PMID 35954274, 2022). "ANGPTL4 plays a tumor suppressive role in HCC, whereas in PDAC and breast cancer it promotes aggressiveness thanks to its effects on endothelial integrity and cellular migration." (PMID 36074318, 2022). "Hypoxia-induced HIF-1 is considered a stimulant of the extravasation of breast cancer to lung cancer via the HIF-1-mediated L1 cell adhesion molecule (L1CAM) and angiopoietin-like 4 (ANGPTL4)." (PMID 36551540, 2022). "Targeting ANGPTL4 is considered a promising strategy to reduce tumor growth in PDAC and metastases formation in breast cancer." (PMID 36074318, 2022). "Hypoxia-induced occupancy of the ANGPTL4 and PDK1 HREs by TRIM28, KU70, KU86, DNA-PKcs, and HIF-1α was also observed in SUM159 human breast cancer cells." (PMID 35031618, 2022). "In this cross-sectional study we investigated the expression of ANGPTL-4 and IGF-1 in primary breast carcinoma tissue samples from young age patients ≤45 years." (PMID 35366286, 2022). "The current study aimed to investigate angiopoietin-like protein 4 (ANGPTL4) and insulin-like growth factor-1 (IGF-1) protein expression in breast tissue from young patients with breast carcinoma." (PMID 35366286, 2022). "More importantly, TGF-β responsive gene ANGPTL4 and CXCL8 that are required for breast cancer lung metastasis and drug resistance were significantly inhibited by resveratrol." (PMID 28827661, 2017). "For example, the TGFβ-Smad pathway induces the expression of interleukin-11 (IL-11), connective tissue growth factor (CTGF), angiopoietin-like 4 (ANGPTL4), and cut-like homeobox 1 (CUTL1) to promote breast cancer invasion and metastasis." (PMID 28356139, 2017). "In breast cancer, extravasation of hypoxic tumor cells into the lung is dependent on HIF-1-regulated expression of ANGPTL4." (PMID 26761211, 2016).
breast cancer (continued). "ANGPTL4 and L1CAM provide two important examples of HIF-induced proteins that have been shown to play a role in the extravasation of breast cancer cells." (PMID 27706047, 2016). "When breast cancer cells are injected via tail vein, HIF-knockdown cells overexpressing ANGPTL4 extravasated more readily to the lungs." (PMID 27706047, 2016). "Angiopoietin-like 4 (ANGPTL4) was also found to be a hypoxia-induced and HIF-dependent gene product that promotes extravasation of breast cancer cells in in vivo models of lung metastasis." (PMID 27706047, 2016). "As a direct target of HIF-1, ANGPTL4 is a candidate for clinical intervention using digoxin, which inhibits HIF-1 and has been shown to decrease tumor growth and lung metastasis breast cancer cell lines and xenografts." (PMID 25999348, 2015). "Since the TGFβ target ANGPTL4 plays a key role in lung metastasis development, we performed a meta-analysis of ANGPTL4 expression relative to WWOX in microarray datasets from breast carcinomas." (PMID 24330518, 2013). "ANGPTL4 inhibits EC (endothelial cell)-EC interactions, whereas L1CAM promotes the adherence of breast cancer cells to ECs." (PMID 23241400, 2012). "Additionally, we constructed an effective prognostic model based on these ECM clusters and recognized ANGPTL4+ and CFD+ fibroblasts as potential biomarkers for immunotherapy in breast cancer." (PMID 40340806, 2025). "Furthermore, correlation analysis unveiled a positive correlation between ANGPTL4 and KLF4 expression in breast cancer specimens." (PMID 40616161, 2025). "Furthermore, we validated ANGPTL4 and KLF4 protein expression in breast cancer patients using immunohistochemistry (IHC) on a tissue microarray comprising of 58 breast cancer samples and 49 adjacent normal breast tissues." (PMID 40616161, 2025). "We observed that, irrespective of obesity status, ANGPTL4 expression was notably elevated in basal-like breast cancer compared to non-basal-like subtypes." (PMID 40616161, 2025). "Future research should further elucidate the specific mechanisms of ANGPTL4 and CFD in breast cancer and develop clinical detection methods and treatment strategies based on these biomarkers, thereby advancing precision medicine in breast cancer." (PMID 40340806, 2025). "In addition, the induction of ANGPTL4 by TGF-β/SMAD signaling was reported to enhance the retention and seeding of breast cancer cells in the lungs." (PMID 38643448, 2024). "In breast cancer cells, the inhibition of HIF (HIF-1α and HIF-2α) resulted in the inhibition of breast cancer tumor growth and lung metastasis by suppressing the expression of angiopoietin-like 4 (ANGPTL4) and L1 cell adhesion molecule (L1CAM)." (PMID 36984785, 2023). "AGAP2-AS1 could be promising predictive biomarker and therapeutic target for HER-2+ breast cancer patients, and AGAP2-AS1 regulated the proliferation and migration of pancreatic cancer partly through suppressing ANKRD1 and ANGPTL4." (PMID 36911393, 2023). "In Roquin2-overexpressing MDA-MB-468 and MCF7 cells, we found that proangiogenic factors mRNA, including PDGFC, ENG, EDN1, and VEGFB, were downregulated in two breast cancer cells, while the mRNA expression of antiangiogenic genes, including TIMP1/3, SERPINF1, and ANGPTL4 were upregulated." (PMID 34345214, 2021). "In addition, in breast cancer, HIF-1-induced angiopoietin-related protein 4 (ANGPTL4) inhibits adhesion between vascular endothelial cells and promotes cancer extravasation." (PMID 32069878, 2020). "For breast cancer, ectopic secretion of MMPs family, such as MMP-1, MMP-2 and MMP-9, as well as VEGF, angiopoietin-like-4 (Angptl4), and COX-2, could degrade and destroy vascular endothelial cell junctions to promote tumor cells metastasis." (PMID 30819235, 2019). "Interestingly, ANGPTL4, PTHLH and SERPINE1 have all been shown to be involved in breast cancer progression and metastasis." (PMID 24330518, 2013).
breast cancer (continued). "Indeed, angiopoietin-related protein 4 (ANGPTL4), a TGF-β1 target gene, disrupts endothelial cell–cell junctions, and facilitates the extravasation of breast cancer cells." (PMID 23967403, 2013). "Therefore, targeted intervention strategies against ANGPTL4 and CFD could emerge as novel approaches to improve breast cancer immunotherapy." (PMID 40340806, 2025). "Therefore, ANGPTL-4 and IGF-1 expressions are common in young breast carcinoma tissue." (PMID 35366286, 2022). "ANGPTL4 has been recognized as an indicator of whether breast cancer will metastasise to the lung, and other studies have indicated that TGF-β primes breast tumours for the seeding of lung metastasis through ANGPTL4 by modulating endothelial integrity to mediate lung metastasis seeding." (PMID 31963541, 2020). "In vitro studies indicated that PPARβ/δ-ANGPTL4 pathway is involved in the regulation of tumor cell invasion and that its pharmacological manipulation by PPARβ/δ strongly inhibits the serum- and transforming growth factor β (TGFβ)-induced invasion of MDA-MB-231 human breast cancer cells." (PMID 29389861, 2018). "Thus, ANGPTL4 secreted by tumor cells in response to TGF-β and released into the circulation increases the permeability of lung capillaries and facilitates the extravasation of disseminated breast cancer cells in a mouse model." (PMID 25968567, 2015). "Given the relevance of ANGPTL4 as a key determinant of lung metastatic phenotypes for breast cancer cells and our observations of a clear inverse behavior between WWOX and ANGPTL4 at the transcript and protein level, we investigated whether this inverse relationship extended to breast cancers." (PMID 24330518, 2013). "Moreover, certain studies have confirmed that ANGPTL4 can promote vascular invasion and distant metastasis of gastric cancer and CRC,22, 23 and transforming growth factor (TGF‐β) can induce ANGPTL4 expression, thereby promoting lung metastasis in breast cancer patients." (PMID 34331381, 2021). "When corrected for subtype and grade, our multivariant analysis shows that high expression of ANGPTL4, a potential druggable target, strongly predicts inferior DFS in young but not older women with basal-type breast cancer." (PMID 25999348, 2015). "Importantly, Elevated ANGPTL4 and KLF4 expression was observed in metastatic breast cancer specimens compared to non-metastatic cases and was positively correlated with poor prognosis." (PMID 40616161, 2025).